DCLRE1C (DNA cross-link repair 1C)
Description:
Nuclease involved in DNA non-homologous end joining (NHEJ); required for double-strand break repair and V(D)J recombination. Required for V(D)J recombination, the process by which exons encoding the antigen-binding domains of immunoglobulins and T-cell receptor proteins are assembled from individual V, (D), and J gene segments. V(D)J recombination is initiated by the lymphoid specific RAG endonuclease complex, which generates site specific DNA double strand breaks (DSBs). These DSBs present two types of DNA end structures: hairpin sealed coding ends and phosphorylated blunt signal ends. These ends are independently repaired by the non homologous end joining (NHEJ) pathway to form coding and signal joints respectively. This protein exhibits single-strand specific 5'-3' exonuclease activity in isolation and acquires endonucleolytic activity on 5' and 3' hairpins and overhangs when in a complex with PRKDC. The latter activity is required specifically for the resolution of closed hairpins prior to the formation of the coding joint. Also required for the repair of complex DSBs induced by ionizing radiation, which require substantial end-processing prior to religation by NHEJ.
Synonyms: ARTEMIS; SCIDA; SNM1C; FLJ11360; A-SCID; DCLREC1C; RS-SCID
Tractability: Small molecule: a structure with a bound ligand is known. PROTAC: ubiquitination databases record sites on it.
Gene: Protein-coding gene on chromosome 10 (14,897,359 to 14,954,432, reverse strand). Ensembl gene ENSG00000152457.
Subcellular location: Nucleus
Subcellular location (Human Protein Atlas): Nucleoplasm; Golgi apparatus
Pathways (Reactome):
DNA Repair: Nonhomologous End-Joining (NHEJ)
Gene Ontology:
Molecular function: 5'-3' exonuclease activity; protein binding; single-stranded DNA endodeoxyribonuclease activity; 5'-3' DNA exonuclease activity; damaged DNA binding; endonuclease activity
Biological process: double-strand break repair via nonhomologous end joining; interstrand cross-link repair; telomere maintenance
Cellular component: nonhomologous end joining complex; nucleoplasm; nucleus
Genetic constraint (gnomAD): Loss-of-function variants: 34 observed, 52.29 expected, observed/expected ratio (o/e) 0.65, 90% interval 0.49 to 0.87. The upper end of that interval is the gene's LOEUF score, 0.87, which puts it in group 3 of 6, group 1 being the genes least tolerant of losing a copy. Missense variants: 779 observed, 783.43 expected, observed/expected ratio (o/e) 0.99, 90% interval 0.94 to 1.05. Synonymous variants: 313 observed, 279.71 expected, observed/expected ratio (o/e) 1.12, 90% interval 1.02 to 1.23.
Gene-disease validity (ClinGen):
ClinGen rates the evidence that DCLRE1C causes each of these diseases.
severe combined immunodeficiency due to DCLRE1C deficiency (autosomal recessive): Definitive. Severe combined immunodeficiency (SCID) due to DCLRE1C deficiency is a type of SCID characterized by severe and recurrent infections, diarrhea, failure to thrive, and cell sensitivity to ionizing radiation.
Homologues: Orthologues: macaque DCLRE1C (91% identical), rabbit DCLRE1C (86% identical), dog DCLRE1C (84% identical), pig DCLRE1C (82% identical), guinea pig DCLRE1C (81% identical), mouse Dclre1c (80% identical), chimpanzee DCLRE1C (79% identical), rat Dclre1c (79% identical), tropical clawed frog dclre1c (59% identical), zebrafish dclre1c (49% identical). Paralogues in human: DCLRE1B (18% identical), DCLRE1A (14% identical).
Diseases named in the same sentence as DCLRE1C in open-access papers:
DCLRE1C is named in the same sentence as 33 diseases in open-access papers, as found by Europe PMC text mining. Sharing a sentence is not in itself a finding about the gene and the disease. The quoted sentences say what the papers report.
severe combined immunodeficiency (7 papers, 2014 to 2025). Severe combined immunodeficiency (SCID) comprises a group of rare monogenic primary immunodeficiency disorders characterized by a lack of functional peripheral T lymphocytes resulting in early-onset severe respiratory infections and failure to thrive. "Biallelic pathogenic variants in another NHEJ gene, DCLRE1C, which encodes ARTEMIS, has been identified in patients with severe combined immunodeficiency, radiation sensitivity and increased predisposition for EBV-associated B cell lymphomas." (PMID 40925926, 2025). "Rare mutations in LIG4 (encoding DNA ligase IV), XLF, DCLRE1C (encoding Artemis) or PRKDC (encoding DNA-PKcs) have been identified in a radiosensitive sub-class of patients with severe combined immunodeficiency (SCID) and can predispose to cancer." (PMID 31921645, 2019). "It is not known whether NK cells from severe combined immunodeficiency (SCID) patients with defective RAGs or DCLRE1C (RAGs−/DCLRE1C−-NK) are active against virus infections." (PMID 31717670, 2019). "Mutations in genes that affect the development or function of T and B cells [DCLRE1C(ARTEMIS), ZAP70, RAG1/2, IL2RG, ILRA7, LIG4, JAK3, ADA] can result in intestinal inflammation along with recurrent infections from severe combined immunodeficiency (SCID)." (PMID 34122435, 2021).
immunodeficiencies (4 papers, 2013 to 2020). "Mutations in the Artemis/DCLRE1C gene have traditionally been associated with SCID and Omenn syndrome, but recently various mutations have been shown to be associated also with milder forms of immunodeficiencies, including hypogammaglobulinemia." (PMID 29888014, 2018). "For the opposite case, u(MA, HA), the gene DSPP, related to deafness and tooth abnormalities (dentin dysplasia and dentinogenesis imperfecta) were found alongside PLAG1, DCLRE1C and PLCB2 to be associated with adenomas, severe immunodeficiency and platelet deficiency respectively." (PMID 29161290, 2017).
Omenn syndrome (3 papers, 2018 to 2023). An inflammatory condition characterized by erythroderma, desquamation, alopecia, chronic diarrhea, failure to thrive, lymphadenopathy, and hepatosplenomegaly, associated with severe combined immunodeficiency (SCID). "One specific example where we improve the prediction of gene–disease associations is for the disease Omenn syndrome (OMIM:603554) which is associated with three genes: DCLRE1C (ENTREZ:64421), RAG2 (ENTREZ:5897) and RAG1 (ENTREZ:5896)." (PMID 37550716, 2023).
breast carcinoma (2 papers, 2012 to 2025). "The three DSB repair genes, BLM, RECQL4 and DCLRE1C, disrupted in the case group all represent attractive breast cancer susceptibility genes." (PMID 22737080, 2012). "TCGA analysis revealed that DCLRE1C (Artemis) mRNA expression was significantly upregulated in the TNBC subtype when compared to other breast cancer subtypes and normal tissue." (PMID 41154337, 2025). "Our analysis of the breast cancer TCGA database revealed that DCLRE1C mRNA expression is significantly higher in TNBC, compared to normal breast tissue and other breast cancer subtypes." (PMID 41154337, 2025). "Based on their biological functions BLM, RECQL4 and DCLRE1C all represent attractive susceptibility genes, although to date clearly deleterious, breast cancer related mutations have not been reported in any of them." (PMID 22737080, 2012).
Fanconi anemia (2 papers, 2013 to 2025). Fanconi anemia (FA) is a hereditary DNA repair disorder characterized by progressive pancytopenia with bone marrow failure, variable congenital malformations and predisposition to develop hematological or solid tumors. "Subsequent work by this group identified JCV protein links to two other DNA repair genes, IEI genes DCLRE1C (gene alias ARTEMIS) and RAD51 (a cause of Fanconi anemia)." (PMID 40761639, 2025).
viral infection (2 papers, 2019). "Our data further identified numerous ribonuclease and deoxyribonuclease genes with unknown roles in viral infection such as Dnase1l3, Dclre1c, Rexo1, Dxo, and Mgme1." (PMID 31057555, 2019).
Artemis) deficiency (1 paper, 2025). "Among the patients with a molecular diagnosis, a female had two diseases, DCLRE1C (Artemis) deficiency, and ichthyosis vulgaris." (PMID 41190063, 2025).
CHARGE syndrome (1 paper, 2024). CHARGE syndrome is a multiple congenital anomaly syndrome characterized by the variable combination of multiple anomalies, mainly Coloboma; Choanal atresia/stenosis; Cranial nerve dysfunction; Characteristic ear anomalies (known as the major 4 C's). "However, OS has also been described in other genetic aetiologies that impair lymphocyte development, including IL7RA, IL2RG, ADA, DCLRE1C, RMRP and LIG4 deficiencies, and CHARGE syndrome." (PMID 38598033, 2024).
gout (1 paper, 2021). A condition characterized by painful swelling of the joints, which is caused by deposition of urate crystals. "PTPRS and DCLRE1C were identified as the most up-regulated and down-regulated genes in gout patients respectively." (PMID 35116032, 2021).
Hypertension (1 paper, 2017). The presence of chronic increased pressure in the systemic arterial system. "Nine SNPs were related (P < 0.01 in any one genetic model) to hypertension, and five of these SNPs (rs150854849 of DCLRE1C, rs202069030 of DUS2, rs139012426 of LOC100505549, rs12229654 at 12q24.1, rs76974938 of C21orf59) were significantly (P < 1.25 × 10−4) associated with this condition." (PMID 28562329, 2017).
tumor (5 papers, 2010 to 2025). "In this study, qRT-PCR showed that the expression levels of two genes, DCLRE1C and ODF4, differed significantly between normal and tumor tissues." (PMID 36339718, 2022). "Out of 11 genes associated with the non-homologous end joining, 4 (i.e., XRCC4, PRKDC, FEN1, and DCLRE1C) display significantly higher expressions in OS tumor samples than normal controls while DNTT has no detectable expression in normal controls." (PMID 35013466, 2022).
DCLRE1C also shares sentences with these, for which no sentence is quoted: cancer (5 papers); infection (3); combined immunodeficiency (2); DiGeorge syndrome (2); adenoma (1); ataxia telangiectasia (1); Autoimmunity (1); B cell lymphomas (1); Bloom syndrome (1); deafness (1); dentin dysplasia (1); dentinogenesis imperfecta (1); eosinophilia (1); ichthyosis vulgaris (1); lymphoma (1); meningeal infections (1); migraine (1); Nijmegen breakage syndrome (1); primary immunodeficiencies (1); sarcoma (1); trisomy 21 (1); xeroderma pigmentosum (1).